AFP (alpha fetoprotein)
Diseases named in the same sentence as AFP in open-access papers (continued):
Sharing a sentence is not in itself a finding about the gene and the disease.
hepatocellular carcinoma (continued). "Fucosylated alpha-fetoprotein (AFP) is widely used in the diagnosis of hepatocellular carcinoma because it is more specific than alpha-fetoprotein." (PMID 24970126, 2012). "Diagnosis is usually made by history, physical examination, imaging (US, CT, MRI), and elevated serum AFP > 400 ng/mL with 75% of hepatocellular carcinoma is multifocal at time of diagnosis." (PMID 22848843, 2012). "In this study AFP had an AUC of 0.916 which makes it a good screening test for the diagnosis of hepatocellular carcinoma." (PMID 22856336, 2012). "The favorable agreement between in vivo tests using SSB and MRI demonstrated the feasibility of in vivo screening using SSB for hepatocellular carcinoma (HCC) targeted by anti-alpha fetoprotein (AFP)-mediated MNPs." (PMID 23056437, 2012). "We successfully achieved animal imaging by injecting human hepatocellular carcinoma cell lines (HCCLM6) that overexpress alpha-fetoprotein (AFP) with antiAFP monoclonal antibody and QD-IgG probes." (PMID 23691472, 2012). "For example, alpha fetoprotein (AFP) is widely used for hepatocellular carcinoma in diagnosis and treatment." (PMID 23028610, 2012). "For example, serum levels of AFP are often elevated in hepatocellular carcinoma (HCC); however, this is also the case in germ cell tumors, gastric, biliary and pancreatic cancers." (PMID 22546315, 2012). "In clinical practice, AFP levels are elevated in various clinical situations, which include hepatocellular carcinoma, acute or chronic viral hepatitis, chronic liver disease, and gonadal tumors." (PMID 22675639, 2012). "Only 26 patients with hepatocellular carcinoma had both positive AFP > 200 ng/ml and SCCA > 0.368 ng/ml." (PMID 22856336, 2012). "Although her serum alpha-fetoprotein was normal, the radiological findings and her clinical history are compatible with hepatocellular carcinoma." (PMID 25374707, 2012). "In our previous study, we used α-fetoprotein (AFP) gene-modified DCs (AFP-DCs) to explore the potential of a DC-based tumor vaccine against hepatocellular carcinoma (HCC)." (PMID 23170121, 2012). "It is reported to be highly sensitive (84.2%) compared to 60% for AFP but has a low specificity (48.9%) for hepatocellular carcinoma." (PMID 22856336, 2012). "The feasibility of this approach has been demonstrated in the story of alpha-fetoprotein (AFP), a marker for hepatocellular carcinoma (HCC)." (PMID 21906357, 2011). "α-fetoprotein (AFP) for hepatocellular carcinoma has 65% sensitivity and 89% specificity, while the addition of VEGF and fucosidase (AFU) tests can increase the sensitivity up to 100%." (PMID 22151235, 2011). "By linking QDs to AFP (alpha-fetoprotein) antibody, an important marker for hepatocellular carcinoma cell lines, a specific immunofluorescent probes was obtained for further detection of AFP antibody in human serum." (PMID 22247690, 2011). "AFP- positive cases have been found among disorders other than hepatocellular carcinoma, such as hepatitis, liver cirrhosis and metastatic cancer of the liver." (PMID 22018031, 2011). "In patient 1, serum AFP, which is known to increase not only during development of hepatocellular carcinoma but also liver regeneration, modestly increased during the rh-HGF dosing period, followed by a gradual decrease during the observation period." (PMID 21548996, 2011). "For hepatocellular carcinoma (HCC), the common methods of screening high risk patients by alpha-fetoprotein (AFP) and ultra-sonography has been shown to result in earlier detection and consequently more easily treatable tumors and longer survival." (PMID 29147241, 2011). "Recently, a hepatoma-specific AFP (HS-AFP) subfraction was reported to be superior to total AFP level in both sensitivity and specificity in differentiating benign liver diseases from malignant ones." (PMID 24281095, 2010).
hepatocellular carcinoma (continued). "hepatoma tissues can synthesize various tumor-related proteins, polypeptides, and isoenzymes, such as alpha-fetoprotein (AFP), hepatoma-specific gamma-glutamyl transpeptidase (HS-GGT), and so on, and then secrete them into the blood." (PMID 20300384, 2009). "Alpha-fetoprotein immunopositivity is encountered in only 37% of hepatocellular carcinomas but this is a more specific immunostain." (PMID 20062599, 2009). "Hepatocellular carcinoma was considered based on the image findings, the elevated level of serum alpha-fetoprotein." (PMID 19918575, 2009). "Serum AFP is a debated, but routinely used marker for hepatocellular carcinoma (HCC) in patients with chronic liver disease." (PMID 18545682, 2008). "This variant of adenocarcinoma has been demonstrated to be an alpha-fetoprotein (AFP)-producing carcinoma arising in extra hepatic organs, and it mimics hepatocellular carcinoma in morphological and functional terms." (PMID 17448253, 2007). "We analysed the sensitivity and specificity of the progressive increase of the levels of alpha fetoprotein for the detection of hepatocellular carcinoma in patients with liver cirrhosis." (PMID 17288606, 2007). "Increased AFP gene expression occurs, for example, in humans suffering from chronic liver disease and was considered to be a marker for hepatocellular carcinoma." (PMID 16822301, 2006). "Further investigations will be necessary for understanding the regulation of AFP gene in rodent models of oval cell proliferation and in human hepatocellular carcinomas." (PMID 16822301, 2006). "In a recent study, AFP was used as an effective tumor rejection antigen to observe its effect in T-cell immune responses, implicating a gene therapy-based strategy for hepatoma cells." (PMID 16080799, 2005). "Hereby, the implication was emerged that AFP functions to constitute one of fundamental steps in the progression of hepatoma." (PMID 16080799, 2005). "We previously reported a specific therapeutic effect of anti-AFP and anti-CEA mouse monoclonal antibody (MAb)-conjugated liposomes containing doxorubicin (DXR) for an AFP-producing hepatoma and a CEA-positive tumour, respectively." (PMID 14562030, 2003). "Five of seven (71.4%) hepatocellular carcinoma patients with alpha-fetoprotein levels less than 20 ng ml−1 produced positive serum DNA test." (PMID 12454776, 2002). "On entry into the study, 53 patients had an AFP concentration > = or 50 ng ml-1 and the 'hepatoma-specific' AFP isoform was detected in 26 of these." (PMID 9010032, 1997). "In 582 consecutive attendees at an outpatient clinic for people with chronic liver disease, a single blood sample was taken for analysis of 'total' AFP and the 'hepatoma-specific' AFP isoform." (PMID 9010032, 1997). "We have evaluated the specificity and sensitivity of detecting hepatoma cells in blood using nested polymerase chain reaction with primers specific for the alphafetoprotein (AFP) gene." (PMID 9062418, 1997). "The high incidence of AFP mRNA in the blood of hepatoma patients supports the notion of early haematogenous spreading of the disease." (PMID 9062418, 1997). "The presence of AFP mRNA in the blood of hepatitis or hepatoma patients suggests the presence of circulating hepatoma cells or hepatocytes in the circulation." (PMID 9062418, 1997). "With the application of 'hepatoma-specific' AFP, the positive predictive value of the test was 73.1%, compared with only 41.5% using the conventional 'total' AFP test." (PMID 9010032, 1997). "Peripheral mononuclear cells from the blood of 20 hepatoma patients were analysed, and 19 patients showed positive AFP mRNA expression." (PMID 9062418, 1997). "The nested polymerase chain reaction amplified a 270-base pair AFP DNA fragment from cDNA of Hep 3B hepatoma cells." (PMID 9062418, 1997). "We conclude that alpha-L-fucosidase is less useful than alpha-fetoprotein as a single marker of hepatocellular carcinoma in southern African blacks." (PMID 2467686, 1989).
hepatocellular carcinoma (continued). "Human alpha fetoprotein (AFP) has been detected by the agar double diffusion method in ascitic fluid, cerebrospinal fluid (CSF) and bile, from fetuses, neonates and patients with AFP seropositive hepatocellular carcinoma." (PMID 4329951, 1971). "When metastases occurred in the lung from a hepatocellular carcinoma producing AFP, the pleural effusions sometimes contained AFP." (PMID 4329951, 1971). "Alpha fetoprotein (AFP) regulates glucose metabolism reprogramming (GMR) related to drug resistance of hepatocellular carcinoma (HCC) and remains unclear." (PMID 42244055, 2026). "In some certain types of cancer, specific tumor markers, for instance, alpha‐fetoprotein in hepatic carcinoma and PSA in prostate cancer, have shown high sensitivity and specificity for specific tumor types, which provides valuable clues for identifying the primary site for CUP." (PMID 40242159, 2025). "However, approximately 75% of patients with hepatocellular carcinoma (HCC) exhibit significantly elevated AFP levels, often reaching as high as 500 ng/mL." (PMID 39942588, 2025). "Additionally, AFP, a fetal plasma protein known for its pleiotropic functions and commonly used as a biomarker for hepatocellular carcinoma, was the most upregulated gene at week 1, showing a 4.41 ± 0.01-fold increase." (PMID 41008923, 2025). "Elevated AFP levels often indicate the presence of hepatocellular carcinoma (HCC)." (PMID 40870838, 2025). "A phase I trial demonstrated that AFP-specific genetic immunotherapy elicited detectable AFP-reactive cytotoxic T-cell responses in patients with hepatocellular carcinoma, confirming the feasibility and immunogenicity of this approach, although no objective tumor regression was reported." (PMID 41614820, 2025). "Alpha-fetoprotein (AFP) is a key serum marker for hepatocellular carcinoma (HCC)." (PMID 40942360, 2025). "This discrepancy may be due to the fact that both AFP and PIVKA‐II were associated with hepatocellular carcinoma in primary HCC patients, thereby establishing a correlation." (PMID 41230775, 2025). "AFP level may be increased in hepatocellular carcinoma and may deprive the proliferation of immune cells, like T-cells and Natural Killer cells, contributing to a declined immune response, tumour growth, and disease progression." (PMID 41514593, 2025). "Sialylated Lewis antigens (sLe^x and sLe^a) are often overexpressed in various cancers, which indicates a poor prognosis, whereas the core fucosylated glycoform of alpha-fetoprotein (AFP-L3) is a more specific biomarker (than serum AFP) for hepatocellular carcinoma." (PMID 40864783, 2025). "Moreover, studies have shown that OPN can serve as a diagnostic marker for hepatocellular carcinoma (HCC), with its sensitivity potentially surpassing that of traditional liver cancer marker alpha-fetoprotein (AFP)." (PMID 41388723, 2025). "In particular, when AFP levels exceed 500 ng/mL, hepatocellular carcinoma can almost be diagnosed." (PMID 39337777, 2024). "Although patients with alpha-fetoprotein-negative hepatocellular carcinoma (AFPNHCC) have a favorable prognosis, a high risk of postoperative recurrence remains." (PMID 38730095, 2024). "Moreover, studies have attempted to add sorafenib to the treatment regimen based on AFP positivity, referring to hepatocellular carcinoma treatment protocols." (PMID 39421450, 2024). "Finally, challenges and further prospects for developing ultrasensitive biosensors for AFP detection and early diagnosis of hepatocellular carcinoma are discussed." (PMID 38785709, 2024). "This research aimed to assess the diagnostic capacity of anti-BIRC5 autoantibody in detecting AFP-negative hepatocellular carcinoma (ANHCC)." (PMID 38832035, 2024). "Alpha-fetoprotein (AFP), a member of the albumin superfamily, is highly abundant in human fetal serum and serves as a tumor-associated biomarker in various cancers, including hepatocellular carcinoma (HCC) and gastric carcinoma." (PMID 39135041, 2024).
hepatocellular carcinoma (continued). "Very high levels of AFP are sporadically observed in patients with intrahepatic cholangiocarcinoma (ICC) and may cause an incorrect initial diagnosis of hepatocellular carcinoma (HCC)." (PMID 39064538, 2024). "The identification of α-fetoprotein (AFP), a biomarker for hepatocellular carcinoma, was conducted utilizing MoS2 modified with an antibody targeting AFP and Au-Ag core-shell nanoparticles attached to a secondary antibody, thus establishing a sandwich-type SERS sensor." (PMID 38544082, 2024). "Some neoplasms, in particular hepatocellular carcinoma and yolk sac tumor, may produce alpha-fetoprotein (AFP)." (PMID 39408649, 2024). "In a multicenter retrospective analysis, CRP and alpha-fetoprotein were found to score immunotherapy in patients with hepatocellular carcinoma treated with atezolizumab in combination with bevacizumab, and patients with AFP ≥ 100 ng/mL and CRP ≥1 mg/dL were found to have a poorer prognosis." (PMID 39741972, 2024). "If a combination of alpha-fetoprotein (AFP) and miR-92b was used for prediction, the accuracy of early hepatocellular carcinoma recurrence prediction after LDLT could be further improved." (PMID 38281957, 2024). "AFP is the most widely used biomarker for the early diagnosis of hepatocellular carcinoma (HCC)." (PMID 39188756, 2024). "For the early detection of hepatocellular cancer, core fucosylation of alpha‐fetoprotein is an approved biomarker, differentiating hepatocellular carcinoma from cirrhosis and chronic hepatitis, thus improving the specificity of alpha‐fetoprotein as a biomarker." (PMID 38223202, 2024). "It is noteworthy that some hepatocellular carcinomas resume expression of foetal albumin (alpha-fetoprotein, AFP), which may represent the reversion of some cancers towards a foetal hepatic state." (PMID 38195504, 2024). "However, some studies have shown that the sensitivity of the AFP test in hepatocellular carcinoma diagnosis is about 60%, and the specificity is only 80%." (PMID 37848835, 2023). "We evaluated whether combining the radiographic tumor burden score (TBS) and alpha-fetoprotein (AFP) level could be used to stratify overall survival (OS) among hepatocellular carcinoma (HCC) patients after liver resection (LR)." (PMID 36831544, 2023). "However, the Cd44 gene status had no influence on either the number of primary liver tumors detected or on the level of the hepatocellular carcinoma biomarker AFP (α-fetoprotein) in the serum of Nf2-mutant mice." (PMID 37174657, 2023). "Alpha-fetoprotein detection aids in the early diagnosis and treatment of hepatocellular cancer." (PMID 37110837, 2023). "AFP is widely established for HCC (hepatocellular carcinoma) diagnosis." (PMID 36979610, 2023). "It has also been reported that SNORD3B‐1 is highly expressed in hepatocellular carcinoma and is utilized as a diagnostic molecular marker for early‐stage hepatocellular carcinoma and AFP‐negative hepatocellular carcinoma." (PMID 37066523, 2023). "For instance, recent reports have demonstrated that AFP may function as a regulator of the phosphatidylinositol 3-kinase/Akt pathway hepatocellular carcinoma cells in humans." (PMID 37588998, 2023). "While in patients with hepatocellular carcinoma, the level of fucosylated, rather than total, alpha-fetoprotein was shown to be more specifically associated with cancer progression, no such specific biomarker currently exists for breast cancer." (PMID 36980181, 2023). "Fucosylated alpha-fetoprotein (AFP-L3) is a specific biomarker for hepatocellular carcinoma." (PMID 37108200, 2023). "However, the AFP level of 400 ng/ml is a set as prejudicial between hepatocellular cancer and chronic diseases such as cirrhosis or hepatitis." (PMID 36793354, 2023). "Abelev discovered the relationship between AFP and hepatoma in 1963." (PMID 36672339, 2023). "Notably, it is important to distinguish an EGCT from hepatocellular carcinoma, hepatocellular carcinoma cells can also express AFP and glypican-3." (PMID 37138865, 2023).
hepatocellular carcinoma (continued). "Interestingly, AFP also faces sensitivity and specificity limitations in diagnosing hepatocellular carcinoma and detecting postoperative recurrence." (PMID 38201440, 2023). "Also, the expression of AFP was completely inhibited in the overexpressed AFP hepatocellular carcinoma cell line (EGHC-9901) by the AFP-siRNA plasmid transfection system through apoptosis." (PMID 38202502, 2023). "CircRNA Cdr1as turned normal liver cells to hepatocellular carcinoma cells and could sponge miR-1270 to regulate AFP level." (PMID 38015711, 2023). "In addition, prognostic factors, such as transforming growth factor beta (TGF-β), alpha-fetoprotein (AFP), and vascular invasion, were highlighted as key indicators of hepatocellular carcinoma progression." (PMID 38201624, 2023). "In addition, PIVKA-II was identified as a potential biomarker to complement AFP in the diagnosis of hepatocellular carcinoma." (PMID 37239939, 2023). "Most guidelines insist surveillance for hepatocellular carcinoma (HCC) of high-risk patients with chronic liver diseases by ultrasonography (USG) every 6 months [with or without alpha-fetoprotein (AFP)]." (PMID 36830919, 2023). "Alpha-fetoprotein was found to be raised in 57.14% of the cases of hepatocellular carcinoma." (PMID 36938225, 2023). "Additionally, they also demonstrated a paper-based lateral flow fluorescence immunoassay (LFIA), using MAFs for the effective detection of alpha-fetoprotein (AFP), a serum biomarker for hepatocellular carcinoma." (PMID 37299780, 2023). "The incidence of microvascular invasion was 28.6%, poor differentiation rate was 9.3%, hepatocellular carcinoma recurrence rate after liver transplantation was 12.1%, and median time to recurrence was 13 months, in the patients with normal alpha-fetoprotein levels." (PMID 37326153, 2023). "Alpha-fetoprotein(AFP) is a cancer biomarker for the diagnosis of hepatocellular carcinoma(HCC); however, its role in macrophage polarization and phagocytosis remains unclear." (PMID 36911723, 2023). "This article aims to an overview of MIPs used for the detection of cancer biomarkers, namely: prostate cancer (PSA), breast cancer (CA15-3, HER-2), epithelial ovarian cancer (CA-125), hepatocellular carcinoma (AFP), and small molecule cancer biomarkers (5-HIAA and neopterin)." (PMID 36835517, 2023). "AFP is a crucial feature of hepatocellular carcinoma, while hepatoid adenocarcinoma is a pathological type of ovarian cancer with a phenotype similar to that of hepatocellular carcinoma." (PMID 36456989, 2022). "AFP is usually elevated in patients with hepatocellular carcinoma and yolk sac tumors." (PMID 35285179, 2022). "AFP is a glycoprotein synthesized from the embryonic yolk sac and liver during pregnancy; in clinical practice, it is most commonly used as a tumor marker for hepatocellular carcinoma." (PMID 36428707, 2022). "In liver cancer, an anti-AFP scFv (alpha-fetoprotein, a hepatocellular carcinoma marker) combined with administered paclitaxel, resulted in a decrease in the density of tumor vessels and a greater decrease in tumor size in mice when compared with only the administration of paclitaxel." (PMID 36077739, 2022). "However, long-term data indicate that the sensitivity of AFP for hepatocellular cancer only ranges from 41% to 65%." (PMID 36612201, 2022). "AFP acetylation plays an important role in hepatocellular carcinoma progression." (PMID 36171897, 2022).